LY75 (lymphocyte antigen 75)
Diseases named in the same sentence as LY75 in open-access papers (continued):
Sharing a sentence is not in itself a finding about the gene and the disease.
cancer (18 papers, 2013 to 2025). A tumor composed of atypical neoplastic, often pleomorphic cells that invade other tissues. "Overall, these results suggest that Ly75 mRNA expression fosters different prognostic effects based on cancer type." (PMID 32397120, 2020). "Owing to the role of Ly75 proteins that are expressed by DCs, various approaches using DC-based cancer immunotherapy have been developed." (PMID 32397120, 2020). "Ly75 expression is also reported to be detected in NK cells, macrophages, DCs, epithelial cells, and cancer cells." (PMID 32397120, 2020). "Accordingly, loading of LY75 with antigens is widely used in vaccination including cancer immunotherapy." (PMID 26871602, 2016). "Next, we decided to verify if shRNA-mediated LY75 gene knockdown could produce any cancer-related phenotypic changes in EOC cells." (PMID 26871602, 2016). "The implication of LY75 in EOC tumorigenesis is poorly understood, although it has been shown that depletion of LY75-positive DCs in mice with established EOC impairs cancer progression." (PMID 26871602, 2016). "In this study, Ly75 expression was confirmed to be positively correlated to the infiltration of immune cells, such as NK cells, CD8+ T cells, and γδ T cells, which are known to act as anti-cancer effector cells." (PMID 32397120, 2020).
infection (18 papers, 2009 to 2024). The state of being infected such as from the introduction of a foreign agent such as serum, vaccine, antigenic substance or organism. "Increased expression of LY75 has been detected within hours after infection by SARS-CoV-2." (PMID 39361370, 2024).
metabolic disease (1 paper, 2024). A congenital disorder (due to inherited enzyme abnormality) or acquired (due to failure of a metabolically important organ) disorder resulting from an abnormal metabolic process. "Studies have shown that LY75 is a susceptibility gene for various cardiovascular and metabolic diseases." (PMID 38809515, 2024).
LY75 also shares sentences with these, for which no sentence is quoted: lung tuberculosis (3 papers); autoimmune disease (2); Granuloma (2); influenza (2); lung carcinoma (2); lymphopenia (2); non-small cell lung carcinoma (2); acute GVHD (1); asthma (1); atherosclerosis (1); B cell lymphoma (1); bile duct adenocarcinoma (1); breast tumors (1); Chorioretinal atrophy (1); chronic hepatitis B (1); CNS tumour (1); colon adenocarcinoma (1); colorectal cancer (1); Crohn disease (1); experimental autoimmune encephalomyelitis (1); gastritis (1); gout (1); heart disease (1); inflammatory bowel disease (1); kidney injury (1); leukemia (1); lipid pneumonia (1); liver diseases (1); liver fibrosis (1); membranous nephropathy (1).
A further 10 diseases each share a sentence with LY75 in 1 paper.